IL6 (interleukin 6)
Diseases named in the same sentence as IL6 in open-access papers (continued):
Sharing a sentence is not in itself a finding about the gene and the disease.
infection (continued). "IL-6, a pleiotropic cytokine, is released by several cell types during infection, cancer, and inflammation." (PMID 39062908, 2024). "The levels of IL-6 and IL-8 in duck serum were noticeably higher in the RA-YM infection group after 24 and 48 h of challenge, compared to both the PBS group and the RA-YM Δomp71 infection group." (PMID 39407352, 2024). "The cytokine, IL-6, plays an important role in mediating host defense in response to tissue injury or infection, and its expression is controlled stringently." (PMID 38521924, 2024). "In pediatric hematology patients, IL-6 and IL-10 have a good predictive value for the diagnosis of serious infections." (PMID 39559703, 2024). "IL-6 is known to increase the number of immune cells in the blood, including neutrophils and lymphocytes, which can help to protect the body against infection during and after exercise." (PMID 39416746, 2024). "Despite showing early lung inflammation but no major histological differences in pulmonary cryptococcosis progression among the experimental groups, IL-6−/− mice had significantly higher blood and brain tissue fungal burden at 7-days post infection." (PMID 39334365, 2024). "IP-10 (CXCL10), TNF-α, and IL-6 were significantly upregulated in response to Delta infection, with concentrations of 3,236, 25.73, and 1,391 pg/mL, respectively." (PMID 38568894, 2024). "Pro-inflammatory cytokines like tumor necrosis factor (TNF), interleukin-1 (IL-1), and interleukin-6 (IL-6) are central to this process, driving the migration of cells to the infection sites." (PMID 39590344, 2024). "PA14 infection induced significant increases in IL-6, TNF and IL-1β in the PA14 + PBS group compared to the Control + PBS group in both lung and BALF." (PMID 39062025, 2024). "The expression of proinflammatory cytokines including Il-6 and Tnf-α was higher in the colons of L-arabinose-treated mice on day 4 post-infection." (PMID 38980058, 2024). "These cytokines are known mediators of inflammation in the context of L. pneumophila infections, and IL-6 and TNFα are highly induced upon infection with the L. longbeachae ΔdotB mutant." (PMID 39259722, 2024). "It induces the aggregation of immune cells, including neutrophils and macrophages, at infection sites, leading to the release of IL-1, IL-6, and TNF-α, promoting inflammation." (PMID 39686447, 2024). "At the same time, secondary infections displayed lower levels of IL-6 and IL-10 during Ph II compared to primary DENV infections." (PMID 39457019, 2024). "Antibiotic treatment significantly reduced kidney signals, correlating with decreased bacterial counts and IL-6 levels, indicating effective infection control." (PMID 39204252, 2024). "Following the infection of macrophages and nanomaterial co-cultures by C. albicans, we evaluated IL-1β, IL-6 and TNF-α transcription levels using RT-qPCR." (PMID 39407477, 2024). "While Wild-type and IL-6−/− brains exhibited a high percentage of ramified microglia early during the infection." (PMID 39334365, 2024). "We measured TNF-α, IL-1β, and IL-6 to confirm the immune system’s activation and the level of infection within the body." (PMID 39066795, 2024). "Markers of inflammation and infection, such as C-reactive protein, interleukin-6, and procalcitonin, also demonstrated significant reductions." (PMID 38790912, 2024). "In this study, we cultured bone-derived chicken dendritic cells (ck-BM-DC) and examined gene expression levels of IFN-α, TLR-3, TLR-7, MHC-I, IL-1β, IL-6, Mx, Casp-3, and Casp-8 pre/post infection with AIV." (PMID 39281683, 2024). "Among them, IL-6 is highly expressed in the early stage of infection, and is reduced after antibacterial intervention." (PMID 38970013, 2024). "Infection with CHIKV also increased the levels of inflammatory cytokines and chemokines (TNF-α, IL-6, IL-10, and CCL-2), which are associated with severity, morbidity, and mortality in patients." (PMID 39339151, 2024).
infection (continued). "Interleukin-6 is a pro-inflammatory cytokine produced by different cells that are expressed during states of cellular stress, such as cancer, infection or inflammation." (PMID 38339059, 2024). "Along the course of infection, there was a reduction in the expression of M1 markers like Nos2, Cd40,Cd86, Tnfa, Nfkb2, Il6 and a corresponding increase in the expression of the M2 markers such as Arg1, Ccl17, Cd206, IL4ra with an exception of Tgfb." (PMID 39693143, 2024). "The mRNA level of IL6 was upregulated at 2 months post-infection in KCs, possibly because of the very complex regulatory mechanism of animals." (PMID 38553755, 2024). "Pro-inflammatory cytokines such as IL-6, tissue necrosis factor (TNF), and IL-17A are necessary for initiating an effective inflammatory process against infection and they are associated with multiple-system organ failure and mortality." (PMID 38969796, 2024). "At the time of fever, the patient’s IL-6 level was 31.00 pg/mL, indicating the presence of mild inflammation or infection." (PMID 39086384, 2024). "Previous reports have investigated that an acute infection response induces rapid production of IL-6, which activates the host defense mechanism against infection through elevated acute-phase proteins and the immune response." (PMID 38616284, 2024). "When we analyzed the values of cytokines IL-6 and IL-10 based on the type of infection (primary or secondary) and the phase of infection, we observed an interesting pattern." (PMID 39457019, 2024). "In comparison with the control group, the expression of Beclin‐1 and LC3 in the infection control group were slightly lower (p > .05), while the levels of PCT, TNF‐α, and IL‐6 in the infection stage group were significantly higher (p < .05)." (PMID 38577990, 2024). "The infection stage group had much higher content of PCT, TNF‐α, and IL‐6 than the infection control group (p < .001)." (PMID 38577990, 2024). "During infection, IL-6 is also N6-methyladenosine modified in the SRE, which is essential for its evasion of SOX." (PMID 38321453, 2024). "STAT3 was originally described as an “acute phase response factor (APRF)” in that it mediates the effects of interleukin-6 (IL-6) and related cytokines in response to tissue injury, inflammation, and infection." (PMID 38611065, 2024). "It has been demonstrated that C. faecalis regulates the production of the cytokines IL-1β and IL-6, thereby coordinating the inflammatory response during infection." (PMID 38671184, 2024). "Local production of cytokines, such as IL1β, IL6 and TNFα help amplify this proinflammatory response, while potent chemokines guide the neutrophils to the infection." (PMID 39509414, 2024). "As an acute inflammatory cytokine, IL-6 is involved in infections; especially in the lungs, and by exerting pyrogenic effects it plays an important role in the onset of infection-related fever." (PMID 37832397, 2023). "Although the serum levels of IL-6 significantly decreased in MFD-fed infected mice compared to MFD-fed uninfected mice, the levels of IL-6 were still significantly greater in MFD-fed infected mice compared to RD-fed infected mice during acute infection." (PMID 36676177, 2023). "When neutrophils before infection were preincubated with pGSN, a significant decrease in IL-4, IL-6, and TNF-α secretion was observed." (PMID 36802172, 2023). "IL-6 and IL-8 levels in the asymptomatic infection group differed significantly between the SFTS patient group and the healthy human group." (PMID 37112920, 2023). "Activated macrophages produce inflammatory mediators such as NO, TNF-α, and IL-6, and increase the inflammatory response at the early stage of infection." (PMID 36768389, 2023). "Nonetheless, potentially dangerous, IL-6-blocking regimens also diminish or abolish the increase of C-reactive protein (CRP) in cases with serious infections." (PMID 37304255, 2023).
infection (continued). "Similar activations mediated by the exogenous PTX3 were also observed on the IL-6 levels that the air pouch exudates after 5 h of HA9801 infection." (PMID 36977278, 2023). "Higher induction of IFNβ and IL-6 secretion by ΔEhaF infection was consistent across multiple MOIs and timepoints." (PMID 37041208, 2023). "The albumin-to-globulin (A/G) ratio and lymphocyte count decreased in cases with mild and moderate infections, while procalcitonin, erythrocyte sedimentation rate, interleukin-6, D-dimer, and C4 levels increased." (PMID 38092887, 2023). "With the E. faecalis 36 clinical isolate, infection induced statistically significant IL-6 and TNF-α levels similar to that secreted in response to UTI89." (PMID 37051302, 2023). "In this study, the PCT, ESR, IL-6, and D-dimer levels were progressively elevated during asymptomatic, mild, and moderate infections." (PMID 38092887, 2023). "The addition of anti-IL-6 antibody resulted in significantly lower infection rates in resting cells stimulated by both IEC − and IEC + (p < 0.001 for both comparisons)." (PMID 37202790, 2023). "IL-6 plays a role both in the host response to tissue damage and infection and as a key factor in promoting inflammatory and autoimmune processes." (PMID 37513733, 2023). "Simultaneously, IL-10 treatment in the late stage of infection effectively mitigated the production of pro-inflammatory factors such as IL-6, INF-γ, and TNF-α at 72 h post-infection, which are consequences of the inflammatory response." (PMID 38035330, 2023). "On the other way, SP-treated cells displayed suppressed production of TNF-α and IL-6 at all time points tested and 48 h post-infection, respectively." (PMID 37280772, 2023). "The expression of some inflammatory molecules (IL-1β, IL-6, IL-12, and TNFα) significantly decreased in the siIRF5-treated group, which differed from that in miR-146b deficiency following CFT073 infection." (PMID 37909731, 2023). "While IL6-STAT3 signaling activators, including IL6, prostaglandin E2 (PGE2), or valproic acid (VPA) significantly increased the infection efficiency and the IL6 transcription." (PMID 37099596, 2023). "Infections due to human respiratory syncytial virus (HRSV) and human bocavirus (HBoV) can mediate the release of several pro-inflammatory cytokines such as IL-6, IL-8, and TNF-α, which are usually associated with disease severity in children." (PMID 37239461, 2023). "SAA is produced in response to proinflammatory cytokines, such as interleukin-6 (IL-6), and is involved in the innate immune response to infection and tissue damage." (PMID 37374228, 2023). "IL-6 is rapidly and transiently expressed when the body perceives stress (infection and tissue damage), promoting the body to respond to stress through inflammatory and immune responses, and IL-6 production ceases when the stress disappears." (PMID 37260523, 2023). "For instance, activated NF-κB translocates to the nucleus, stimulating the secretion of inflammatory factors such as IL-1β, TNF-α, and IL-6, thus aggravating the inflammatory response after infection." (PMID 36979335, 2023). "This study would provide evidence of the changes in the proportions of T and B lymphocyte populations in cancer patients relative to the current infection state along with the proinflammatory cytokine profiles of IL-1, IL-6, and TNF-α." (PMID 37068081, 2023). "The results in serum showed that the level of pro-inflammatory cytokine IL-1β and IL-6 dramatically increased and the level of anti-inflammatory cytokine IL-10 considerably dropped after CsA infection." (PMID 38259457, 2023). "We believe that a “controlled” infection with a modified version of SARS-CoV-2 along with the administration of IL-6 blockers and PD-L1 checkpoint inhibitors can promote the regression of several different difficult-to-treat aggressive malignancies." (PMID 36768649, 2023).
infection (continued). "In contrast to amniotic fluid, IFN‐β, IL‐10, IL‐6, and IL‐27 levels were undetectable in response to infection, and TNF‐α levels were decreased albeit barely above the limit of detection." (PMID 37259639, 2023). "Regarding cytokine production, ELISA analysis further demonstrated that both cKp and hvKp infection greatly enhanced the release of IL-6, TNF-α, and IL-1β in macrophages." (PMID 37223846, 2023). "Furthermore, thymo-suppressive cytokines such as IL-6, oncostatin M, and leukemia inhibitory factor increased, and thymo-stimulative cytokines such as IL-7 decreased, diminishing naïve T-cell output and increasing the susceptibility to infection, autoimmunity, and cancer." (PMID 37654571, 2023). "Monocytes are recruited to the site of infection during the early phase by IL-6, IL-8, CCL2, CCL5, and MIP-1α derived from infected AECs and macrophages." (PMID 37896776, 2023). "Our findings suggest that this is also true for community-acquired infections as the subjects who cleared infection had significantly higher levels of IL-1, IL-6, FGF2, and IFN-gamma." (PMID 37973814, 2023). "Pre-infection of BM-DCs by one or both mycoplasmas induced, in general, similar levels of IL-6 and CXCL8 to those induced by S. suis alone." (PMID 37513713, 2023). "Both the upper and lower airways responded to the infection by all VoCs, but with a tissue-specific inflammatory signature: in the lungs, Mx2, Il-6, Cxcl10 and Il-10 were upregulated for all VoCs, and the highest in SARS-COV-2 Wuhan-infected animals." (PMID 37495586, 2023). "All septic animals showed reduced WBC counts as early as 2 h after infection compared to the preoperative concentrations, as well as increased serum concentrations of interleukin-6 (IL-6) and tumor necrosis factor-alpha (TNF-α)." (PMID 37371588, 2023). "Infection with EcoHIV caused a significant increase in the secretion of MCP-1, RANTES, and IL-6 by more than 50% as compared to brains exposed to PBS control." (PMID 36831299, 2023). "In line with previous findings, we showed higher fold changes in IL-6 levels after infection in TLR2−/−/young mice compared with WT/young mice." (PMID 36808423, 2023). "This indicates that enhancements in serum concentrations of IL-6 and sIL-6R during infection lead to an increased agonistic trans-signaling mechanism." (PMID 37887780, 2023). "Meanwhile, our results also revealed that the presence of the capsule effectively induced an inflammatory response (i.e., increased IL-6 and IL-8 levels) following infection with K2044, K2044K1wcaJ, and K2044K2wcaJ strains." (PMID 37180440, 2023). "IL-6 is generated at sites of infection and inflammation by immune cells, adipocytes, and endothelial cells." (PMID 37095536, 2023). "BMmacs derived from Tln1fl/fl and Tln1Δmye mice displayed similar levels of induced Tnf, Il1b, Il6, and Il23a transcripts after infection with C. rodentium." (PMID 38102166, 2023). "In contrast, IL-6 was released in large amounts in septic patients, confirming its use as a marker of infection." (PMID 37240374, 2023). "The produced cytokines, tumor necrosis factor (TNF), interleukin 6 (IL-6), and interleukin 1 (IL-1), also trigger local cellular responses to injury or infection and fever development." (PMID 36865749, 2023). "aureus, Δlgt S. aureus induced low levels of PGE2, IL-1β, IL-6, IL-10, and IL-8 secretion into neutrophil supernatants after infection of neutrophils for 9 h at MOI 3:1 and MOI 10:1 (P < 0.01, P < 0.001)." (PMID 37168122, 2023). "Infection by T. rubrum was shown to stimulate the activation of nuclear factor kappa beta (NF-κB) and the production of IL-1β, IL-6, TNF-alpha and IL-10 by macrophages." (PMID 36838531, 2023).
infection (continued). "qPCR and Multiplex immunoassay performed in lung homogenates confirmed that, in line with cytospin analysis, infection at ZT12 was associated with lower levels of expression of pro-inflammatory cytokines TNFα, IL-6, and IL-1β and the chemokine CXCL1." (PMID 36896128, 2023). "The down-regulation of major cytokines after PM or PA infection (namely, IL-6) was notable, considering the extensive damage and cytotoxicity caused." (PMID 37939183, 2023). "It is also known that during infection, immune system upregulates the concentration of main pyrogenic cytokines such as IL-6, IL-1β and TNF-α that mediate the fever response." (PMID 37849757, 2023). "Elevated inflammatory marks, such as white blood cell count, CRP, PCT, or IL-6, also suggest the possibility of concurrent infection." (PMID 38444540, 2023). "Pre-sensitization of macrophages with exosomes prior to infection was shown to increase IL-1β and IL-6 levels." (PMID 37841240, 2023). "This sterile protection which occurred 30 or 60 days after the second IL-6 Tg-PbANKA/LISP2 SPZ infection strongly suggests the induction of a robust memory response." (PMID 37143657, 2023). "In most cases, the addition of anti-IL-6 antibody reduced the infection rates to the level of unstimulated resting CD4 + T cells, suggesting that IL-6 was necessary for the effect of IEC stimulation." (PMID 37202790, 2023). "The results suggest that early after infection, IL-6 controls the production of NO, which regulates the levels of NT on CD8 T-cells modifying their effector functions." (PMID 37818368, 2023). "The odds of the continued duration of infection increased by 26% for each unit increase in concentrations of serum IL-6." (PMID 36679958, 2023). "Coinciding with these in vitro results, in vivo murine peritoneal challenge assays showed high increase of IL-6 and improved bacterial clearance in response to infection by the ΔrelAΔspoT double mutant strain." (PMID 36937293, 2023). "At 24 h the IL-6 level was increased significantly by 142%, p < 0.0002 compared to 12 h post infection." (PMID 36707891, 2023). "After infection with A. hydrophila, pathological observation showed that il-6−/− zebrafish exhibited milder liver damage than wild-type (WT) zebrafish." (PMID 38139043, 2023). "Regarding IL-6, infection decreased this cytokine particularly in the infected group treated with letrozole + testosterone." (PMID 37384220, 2023). "This induction aligns with a previous study showing that RA prolongs the increased expression of IL6 in macrophages following a pro-inflammatory stimulus, suggesting a better physiological response against infection agents." (PMID 37762456, 2023). "We noticed increased levels of IL-6 at later time points post infection in both BV2 and Neuro2A cell line." (PMID 36707891, 2023). "TNF-α, IL-1β, and IL-6 levels showed a significant positive correlation with the severity of infection (r = 0.660, 0.539, and 0.495, respectively)." (PMID 37068081, 2023). "Early after infection, IL-6 drives hepatic synthesis and secretion of acute-phase reactants, which orchestrate the systemic immune response." (PMID 37818368, 2023). "The infection markedly increased the expression of IL-6 and RANTES, a chemokine mainly released by flow-dependent platelets." (PMID 37446229, 2023). "Increased IFN-γ, IL-6, and KC levels occurred in the lungs by 48 hours post infection after i.n. compared to i.d. infection consistent with higher bacterial loads in this tissue following i.n. infection." (PMID 37883420, 2023). "A cross-sectional study from Nigeria showed a significant reduction of IL-10 and IL-6 in co-infected patients compared to TB mono-infection." (PMID 38089636, 2023). "Increased levels of IL-1, IL-6 and TNF are often detected in several tissues during acute ASFV infections and associated with lymphoid depletion, hemorrhages and oedemas." (PMID 36680273, 2023).